CYP11B2 (cytochrome P450 family 11 subfamily B member 2)
Diseases named in the same sentence as CYP11B2 in open-access papers (continued):
Sharing a sentence is not in itself a finding about the gene and the disease.
adenoma (continued). "In our case, immunohistochemical analysis and mRNA levels of steroidogenic enzymes revealed a left adenoma that primarily consisted of clear cells and mainly expressed CYP11B2, whereas the right adenoma was composed of both eosinophilic compact and clear cells and mainly expressed CYP11B1." (PMID 36960396, 2023). "In case 13, two nodules with clear borders that were similar to adenomas neither expressed CYP11B2 nor harbored KCNJ5 mutations." (PMID 35492351, 2022). "CpG dinucleotides in the CYP11B2 promoter are hypomethylated in aldosterone-producing adenomas." (PMID 33925539, 2021). "Of the 19 patients, 16 had CYP11B2-positive adenomas, which were considered APAs." (PMID 29899838, 2018). "The molecular expression of CYP11B2 and gonadal receptors in adenomas were also explored." (PMID 28102204, 2017). "Furthermore, immunohistochemical analysis revealed a site of strong CYP11B2 expression in the vicinity of the adenoma, which was thought to be an APCC and might have been the responsible lesion." (PMID 39027636, 2024). "Likewise, in the present case, DNA methylation at the promoter region of CYP11B2 might have been observed in the CYP11B2-deactivated adenoma." (PMID 39027636, 2024). "In addition, the adenoma with the PRKACA p.Leu206Arg mutation can be negative for CYP11B2 (aldosterone synthase) immunostaining indicating the likely function of this mutation in tumor formation." (PMID 36004349, 2022). "Therefore, it could potentially be the reason for the high aldosterone production seen in patients with KCNJ5-mutant APAs despite the low expression of CYP11B2 in the adenoma." (PMID 27777363, 2016). "In this study, we observed a strong co-localization of aldosterone synthase (CYP11B2) and CXCR4 in aldosterone-producing adenoma and other aldosterone-producing lesions." (PMID 42290661, 2025). "Our study included a review of 20 previously documented cases of aldosterone- and cortisol-producing adenomas (A/CPAs), two of which were concurrently positive for both CYP11B1 and CYP11B2, consistent with our findings." (PMID 39010034, 2024). "The question whether the gain-of-function mutations driving CYP11B2 autonomy are the same as cause the adenomas has not been settled, and there may indeed be a fine balance between cell growth and death depending on the mutation and/or expression level of the mutated channel." (PMID 39170743, 2024). "These adenomas exhibited cytoplasmic and/or nuclear beta-catenin expression as well as a variable expression of CYP11B1 (typically expressed in ZF layer) and CYP11B2 (typically expressed in ZG layer) by immunohistochemistry." (PMID 29594118, 2018). "This is consistent with previous findings showing that CYP11B2 mRNA levels do not always correlate with aldosterone production in aldosterone-producing adenomas, likely due to post-transcriptional and enzymatic regulatory mechanisms." (PMID 40533529, 2025). "Conversely, CYP11B1 score was higher in those with a CYP11B2-negative adenoma than in the remaining patients (120.0 (10.0–90.0) vs 30.0 (70.0–180.0), P < 0.001)." (PMID 38051154, 2024). "Of the 48 patients with a CYP11B2-negative adenoma, 93.8% had biochemical cure, while biochemical cure was achieved in 68.9% of the 61 patients with no adenoma (P = 0.001)." (PMID 38051154, 2024). "Functional subtyping methods decrease the operations of CYP11B2-negative adenomas and are superior to anatomical imaging in identifying unilateral primary aldosteronism." (PMID 38051154, 2024). "Although immunohistochemistry for CYP11B2 was negative in adenoma, an aldosterone-producing cell cluster was confirmed in the adjacent left adrenal gland." (PMID 39027636, 2024). "The expression of CYP11B2 in pheochromocytomas and non-functioning adenomas (NFAs) (n = 4) was also studied." (PMID 39596027, 2024). "In the non-APA group, 48 patients (43.6%) had a CYP11B2-negative adenoma, while 62 (56.4%) had no adenoma present according to the re-evaluated H&E staining." (PMID 38051154, 2024).
adenoma (continued). "Every fifth of these cases turned out to be CYP11B2-negative adenomas, while this was the case for only every tenth patient in the pooled functional method group." (PMID 38051154, 2024). "Although no current method of assessing the lateralization of aldosterone overproduction is without limitations, we found higher clinical cure rates and lower prevalence of CYP11B2 negative adenomas among those who underwent functional lateralization studies." (PMID 38051154, 2024). "Clinical cure rates were lower and CYP11B2-negative adenomas more common after adrenalectomy based on anatomical imaging than functional studies." (PMID 38051154, 2024). "They found that the methylation rates of CYP11B2 were decreased in APAs compared with non-functioning adenomas." (PMID 36982850, 2023). "No increase in Ang II-stimulated CYP11B2 or aldosterone production was seen in cells adjacent to the cortisol-producing adenoma (Adr 5)." (PMID 37291193, 2023). "Strong CYP11B2 staining in the adenoma confirmed aldosterone source from this adenoma without any positive adjacent nodular hyperplasia." (PMID 36926028, 2023). "When that time arrives, molecular imaging offers the potential advantages over AVS of localization as well as lateralization, given our examples of patients in whom the largest nodule on CT was not the [11C]metomidate-avid, CYP11B2-positive adenoma." (PMID 36646800, 2023). "In patients where MTO predicted a mixture of functional and non-functional adenomas, with respectively high and low [11C]metomidate uptake, IHC confirmed large differences in CYP11B2 expression between adjacent adenomas." (PMID 36646800, 2023). "The histopathological characterization of aldosterone and cortisol co‐secreting adenoma could show ZF and ZG like cells, respectively, while CYP11B1 and CYP11B2 immunostaining demonstrated heterogeneity." (PMID 34657370, 2021). "The endoplasmatic reticulum carrier Calmegin (CLGN) is also upregulated in APAs compared to non-functioning adenomas, with a clear positive correlation with CYP11B2 expression." (PMID 34771744, 2021). "CYP11B2 expression was supposed to be positive in true adenomas and be negative in non-functional adenomas." (PMID 34572353, 2021). "The remaining one patient showed neither positive CYP11B2 immunostaining adenoma nor APCC on his section." (PMID 34631800, 2021). "The CYP11B2 (aldosterone synthase) and CYP17A1 mRNA expressions were significantly higher in both the A/CPA and pure APA tumors than in the normal adrenal cortex, indicating that the excess aldosterone and cortisol did come from the adenomas in these patients." (PMID 29770148, 2018). "Moreover, CYP11B2 positive immunostaining in tumor cells distinguishes an APA from a nonfunctioning adenoma." (PMID 39946402, 2025). "This might partially be explained by the higher CYP11B1 scores in adrenal samples with CYP11B2-negative adenomas, implicating possible cortisol cosecretion." (PMID 38051154, 2024). "Interestingly, a higher rate of biochemical cure was achieved in patients with a CYP11B2-negative adenoma compared to those with no adenoma." (PMID 38051154, 2024). "Here, we reclassified the samples to APA, APN, APM, APDH and to CYP11B2-negative adenomas." (PMID 38051154, 2024). "More research studies are needed to determine whether CYP11B2-negative nodules are hyperplastic nodules, non-functional adenomas, or potential/silent aldosteronoma inhibited by other CYP11B2-positive nodules." (PMID 35492351, 2022). "The IHC showed condensed CYP11B2 staining in the adenoma, but not in the peri-tumoral region." (PMID 34572956, 2021). "Lesions did not include non-functional adenomas because those were not positive for CYP11B2." (PMID 33437027, 2021). "Interestingly, one patient with adenoma showed no expression of CYP11B2 in the tumor but had multiple CYP11B2-expressing APCCs." (PMID 31695023, 2019).
adenoma (continued). "In contrast, tumors that are composed predominantly of ZG-like compact cells are typically enriched in ATP1A1-, ATP2B3-, and CACNA1D-mutant aldosterone-producing adenomas that show increased and strong CYP11B2 expression and predominantly negative CYP11B1 or CYP17A1 expression profiles." (PMID 29594118, 2018). "In MATCH, we compared the in vivo uptake of [11C]metomidate into APAs, non-aldosterone-producing adenomas and the adjacent adrenal, correlating with measurements of CYP11B1 and CYP11B2 expression of each region by quantitative PCR or RNA-seq." (PMID 36646800, 2023). "Given that previous studies have reported a negative correlation between adenoma size and CYP11B2 expression and a positive correlation between the expression level of CXCR4 and CYP11B2, the expression density of CXCR4 in micro-APA should theoretically be higher than that in macro-APA." (PMID 40084145, 2025). "However, immunohistochemistry reveals that APA consists of CYP11B2-positive cells, CYP11B1-positive cells, and double negative cells, whereas non-functional adenomas only comprise CYP11B1-positive cells and double negative cells and did not harbor CYP11B2-positive cells." (PMID 33437027, 2021).
primary aldosteronism (18 papers, 2014 to 2026). An endocrine disorder characterized by excessive production of aldosterone by the adrenal glands. "In the past decade, the development of specific CYP11B2 antibodies and the discovery of the aldosterone driver mutations have largely progressed our understanding of primary aldosteronism." (PMID 36012306, 2022). "Recently, there is considerable interest in understanding the possible role of the CYP11B2 gene with corticosterone methyl oxidase deficiency, primary aldosteronism, and cardio-cerebro-vascular diseases." (PMID 25102047, 2014). "Then, it is of considerable interest that the pathogeny of some cardiovascular disease but not limited to primary aldosteronism could be the variants in the CYP11B2 gene, and aldosterone may act as a central player in this pathological process." (PMID 25102047, 2014). "The findings indicated that the aldosterone‐producing enzymes HSD3B2 and CYP11B2 were both upregulated in Conn's syndrome and non‐functional ACAs, suggesting that hormone synthesis and secretion abnormalities are associated with ACAs." (PMID 40190189, 2025). "Incorporating CYP11B2 staining in histopathological diagnosis enhances the prediction of surgical outcomes in primary aldosteronism." (PMID 38051154, 2024). "The discovery of the KCNJ5 somatic mutation in aldosteroene producing adenoma (APA) in 2011 and the development of specific CYP11B2 antibodies in 2012 have greatly advanced our understanding of the pathophysiology of primary aldosteronism." (PMID 36012306, 2022). "Histological examination of the resected tumor with anti-CYP11B2 antibody indicated that she had a vascular endothelial cyst with primary aldosteronism (PA) due to multiple adrenocortical micronodules." (PMID 33688442, 2021). "High rates of adrenal pathology, especially CYP11B2-positive findings and possibly pheochromocytomas, could have implications for the prevention of sudden death, as low-cost biochemical screening for primary aldosteronism and pheochromocytoma is available." (PMID 39995489, 2025). "Subtype classification based on CYP11B2 immunostaining result of unilateral primary aldosteronism." (PMID 34631800, 2021). "In recent years, there is considerable interest in understanding the possible role of the CYP11B2 gene for assessing the risk associated with corticosterone methyl oxidase deficiency (including CMO I and CMO II), primary aldosteronism, and cardio-cerebro-vascular diseases." (PMID 25102047, 2014). "Expression of CYP11B2 was discontinuous, as often seen with increasing age in humans, with clustering of aldosterone‐producing cells in distinctive (micro‐)nodules, which may contribute to cases of primary aldosteronism." (PMID 39877942, 2025). "A 29-year-old female patient diagnosed with primary aldosteronism (PA) in 2004 underwent complete adrenalectomy for left aldosterone-producing adenoma (APA) confirmed by hematoxylin and eosin (HE) and CYP11B2 staining." (PMID 34630330, 2021). "Metomidate is an inhibitor of the enzyme 11β-hydroxylase (CYP11B1) and aldosterone synthase (CYP11B2), which are found in the adrenal cortex, and 11C-labeled metomidate ([11C]MTO) is currently used for imaging of adrenocortical carcinoma and primary aldosteronism (PA)." (PMID 39325320, 2024). "The non-tumorous adrenal cortex often exhibits aldosterone-producing cell clusters (APCCs) and paradoxical ZG layer hyperplasia to justify the unilateral source of primary aldosteronism in the absence of other CYP11B2-expressing adrenal cortical proliferation." (PMID 29594118, 2018). "Understanding the functional and cellular correlates of the previously discussed ion channel-related molecular alterations has transformed the field of primary aldosteronism by expanding the role of biomarkers including but not limited to CYP11B2, CD56, and Dab2." (PMID 29594118, 2018).
primary aldosteronism (continued). "All these 24 non-APA had CYP11B2-stained cell clusters at the subcapsular portion of peri-tumoral regions or adjacent para-tumoral tissue, in term of aldosterone-producing nodules (APN) or APM according to the HISTALDO (histopathology of primary aldosteronism) consensus." (PMID 34572353, 2021).
adrenocortical adenoma (16 papers, 2017 to 2025). "CYP11B1 were expressed in the bilateral adrenocortical adenomas, and CYP11B2 was also expressed in the right adrenocortical adenomas." (PMID 38017509, 2023). "The immunohistochemistry for CYP11B2 has become an important tool to indicate the excessive production of aldosterone and to identify the location of aldosterone-producing cells in adrenal adenoma or other parts of adrenal tissues." (PMID 34440230, 2021). "Lower expression of MIR193A was observed in human aldosterone-producing adrenocortical adenomas, and was functioned as a tumor suppressor by targeting and restraining CYP11B2 expression both at mRNA and protein level." (PMID 31523496, 2019). "The aldosterone synthesis could possibly be suppressed by the DNA methylation of CYP11B2 in unilateral PA with adrenocortical adenoma." (PMID 39027636, 2024). "The pathological report indicated adrenocortical adenoma, and immunohistochemistry showed diffuse homogeneous expression of CYP11B1 and CYP11B2." (PMID 38017509, 2023). "Finally, it needs to be stated that even surgical treatment does not yield a final diagnostic gold standard because while the pathologist can determine that there is an adrenocortical adenoma, performing immunohistochemistry for CYP11B2 (aldosterone synthase) is not a diagnostic standard." (PMID 37444604, 2023). "The right adrenal adenoma showed CYP11B1-negative and CYP11B2-positive staining and harbored the KCNJ5-L168R mutation." (PMID 35399924, 2022). "In 2014, a mouse monoclonal antibody against aldosterone synthase (CYP11B2) was established, which made it possible to study the function of adrenal adenoma." (PMID 34552553, 2021). "The study revealed 2 kinds of adrenocortical adenomas in 1 adrenal tissue: adrenocortical adenoma with CYP11B2 activation or without activation." (PMID 39027636, 2024). "In such cases, APA can be below the detection limit of imaging studies and/or imaging-detected tumors can be non-functioning adrenocortical adenomas (CYP11B2-negative tumors by IHC)." (PMID 34267727, 2021). "Calneuron 1 (CALN1), localized in the endoplasmatic reticulum, binds calcium ions and positively correlates with the increased CYP11B2 expression in APAs in comparison to non-functioning adrenal adenomas." (PMID 34771744, 2021). "Imaging agents for these targets (CXCR-4 and CYP11B2) have the advantage of identifying adrenal adenomas based on the expression/overexpression of targets not generally seen in normal adrenal tissue, and likely have clinical utility for primary aldosteronism detection." (PMID 35483964, 2022). "One patient showed APCC in the ZG with CYP11B2-negative unilateral adrenocortical adenomas." (PMID 34631800, 2021).
hyperaldosteronism (14 papers, 2015 to 2025). Overproduction of aldosterone by the adrenal glands, which may lead to hypokalemia and/or hypernatremia. "Patients with tumors carrying ARMC5 variants presented with varying levels of hyperaldosteronism, low-renin hypertension, and decreased expression of CYP11B2." (PMID 33800142, 2021). "Concurringly, APCCs were also reported to be increased in adrenals of unilateral CT-negative PA compared to normotensive adrenals, implying that the elevated number of adrenal CYP11B2-expressing nodules might be the cause of hyperaldosteronism in these patients." (PMID 33763031, 2021). "We aimed to identify the diagnostic, functional and prognostic value of CYP11B2, CYP11B1, and β-catenin immunostaining in unilateral hyperaldosteronism." (PMID 34631800, 2021). "The lower expression of CYP11B2 was possibly compensated by the increased adrenocortical mass, leading to hyperaldosteronism." (PMID 33800142, 2021). "Glucocorticoid remediable aldosteronism (GRA), also known as familial hyperaldosteronism type 1 (FH-I), is a result of the chimeric CYP11B1/CYP11B2 gene, which causes an ectopic expression of aldosterone synthase activity under the regulation of ACTH, resulting in hyperaldosteronism." (PMID 35054115, 2022). "The presence of CYP11B2 supports that synthesis of aldosterone can occur in these cell clusters and therefore might contribute to hyperaldosteronism." (PMID 33763031, 2021). "These facts may suggest that (P)RR, as well as CYP11B2, is a determinant of tumor aldosterone production and clinical manifestations of hyperaldosteronism in APA." (PMID 33061968, 2020). "Compounds from the two studied series (7-benzyloxy and 7-aryloxy derivatives) were selected and tested towards CYP11B1 (steroid 11β-hydroxylase, drug target for Cushing’s syndrome, or metabolic disease) and CYP11B2 (aldosterone synthase, drug target for hyperaldosteronism and congestive heart)." (PMID 29382051, 2018). "An unequal crossover event between these genes can result in a gene variant with a CYP11B1 regulatory element and CYP11B2 catalytic sequence, i.e. regulated by ACTH but coding for aldosterone synthase activity, resulting in glucocorticoid-suppressible hyperaldosteronism." (PMID 27293689, 2015). "A study on 107 adrenal glands of normotensive Japanese patients from an 837 consecutive autopsy cohort was conducted to test the hypothesis that hyperaldosteronism in the group of CT-negative PA patients was induced by the elevated number of adrenal CYP11B2-expressing nodules." (PMID 33763031, 2021).